CD34 (CD34 molecule)
Diseases named in the same sentence as CD34 in open-access papers (continued):
Sharing a sentence is not in itself a finding about the gene and the disease.
angiosarcoma (continued). "Previous flow cytometric and immunocytochemical analysis of hemangiosarcoma samples from Golden Retrievers and from non-Golden Retrievers showed expression of levels of CD133, CD34, c-Kit, CD45, CD146, and αvß3-integrin were equivalent." (PMID 19461996, 2009). "Interestingly, there was no expression of CK AE1/AE3, S100, PLAP, LCA, CD34, and factor VIII which is notable, as the article suggests factor VIII is commonly expressed in angiosarcomas." (PMID 40542819, 2025). "Epithelioid angiosarcoma is positive for CD31, but it is classically negative for CD34." (PMID 22943673, 2012). "However, the CD34 antibody is not specific for SFT diagnosis and can be positive in angiosarcomas and gastrointestinal stromal tumors." (PMID 22192457, 2011).
myocardial infarction (77 papers, 2009 to 2025). Gross necrosis of the myocardium, as a result of interruption of the blood supply to the area, as in coronary thrombosis. "In support, plasma VEGF is strongly associated with the mobilisation of CD34+ cells that occurs with myocardial infarction." (PMID 39476319, 2025). "The CD34+ cell culture technique (QQc) was shown to upregulate gene profiles related to angiogenesis and anti-inflammation in a rat model of myocardial infarction treated with CD34+ cell-enriched regeneration-associated mononuclear cells." (PMID 41294818, 2025). "In humans, decreased levels of circulating CD34+ cells are linked to more severe coronary artery disease and worse outcomes following myocardial infarction, and higher mortality." (PMID 36660500, 2022). "In preclinical myocardial infarction models, isolated CD34+ cells were associated with improvements in overall myocardial performance and regional wall motion, and they showed potential in reducing fibrosis and increasing angiogenesis." (PMID 32823683, 2020). "More recent studies also showed that CD34+ PB PCs were associated with myocardial infarction and death in patients undergoing coronary angiography and patients with Type II Diabetes." (PMID 30929097, 2019). "In patients with ischemia or myocardial infarcts, BM-MNCs or specific subtypes, such as CD34+ cells, are used to promote angiogenesis, with mixed outcomes." (PMID 40140186, 2025). "CD34+ cells have been utilized to enhance heart regeneration following myocardial infarction, although the treatment outcomes have been variable 33-35." (PMID 39990233, 2025). "From the end of 2002, our group conducted a Pilot study using immuno-selected autologous peripheral-blood (PB) CD34+ cells in a small cohort of patients who had experienced a heart attack with poor prognosis." (PMID 37861968, 2024). "For example, bone marrow derived CD34+VEGFR3+ progenitor cells are claimed to be able to differentiate into LECs to increase cardiac lymphangiogenesis in the adult rat model after myocardial infarction." (PMID 38505621, 2024). "The effectiveness of CD34 + cell implantation in the treatment of myocardial infarction (MI) has been confirmed." (PMID 37038215, 2023). "Ex vivo monitored human CD34+ stem cells (SCs) injected into myocardium scar tissue have shown real benefits for the recovery of patients with myocardial infarctions." (PMID 37298503, 2023). "We have previously shown that intracardiac delivery of autologous CD34+ cells after acute myocardial infarction (AMI) is safe and leads to long term improvement." (PMID 37952030, 2023). "In particular, a favorable improvement in left-ventricular (LV) function in a rat model of myocardial infarction (MI) after intravenous injection of ex vivo expanded human CD34+ cells was reported." (PMID 35886888, 2022). "The authors reviewed the potential utility of CD34+ cell transplantation in acute myocardial infarction, refractory angina, and ischemic heart failure." (PMID 36660500, 2022). "After adjustment for age, sex, race, body mass index, smoking, and previous myocardial infarction, a shorter LTL was associated with lower CD34+ cell levels; for every 10% shorter relative LTL, CD34+ levels were 5.2% lower (p-value < 0.001)." (PMID 35886017, 2022). "Myocardial perfusion measured by single-photon emission computed tomography (SPECT) improved and myocardial infarct size by gadolinium-enhanced cardiac magnetic resonance imaging (MRI) decreased at 6 months after CD34+ cell transplantation." (PMID 36644256, 2022). "Transplantation of autologous CD31+ and CD34+ cells induced neovascularization and improved ventricular function after myocardial infarction in pig and rat models." (PMID 34203711, 2021). "Patients with acute myocardial infarction have been shown to have a large number of circulating EPCs and CD34+ mononuclear cells post-infarction." (PMID 33193725, 2020).
myocardial infarction (continued). "Two hours post-myocardial infarction (MI) we observed a drop in the circulating levels of the CD34 and CD133 positive cells, which was returned to normal levels by 24 h post-MI and these levels were sustained up to 14 days post-MI." (PMID 28928656, 2017). "The aim of the present study was to isolate mesenchymal stromal cells (MSC) with CD105+CD34- phenotype from human hearts, and to investigate their therapeutic potential in a mouse model of hindlimb ischemia and myocardial infarction (MI)." (PMID 27415778, 2016). "The aim of the present study was to investigate therapeutic potential of human MSC with CD105+CD34- phenotype in a mouse model of hindlimb ischemia and myocardial infarction." (PMID 27415778, 2016). "The same group performed another study evaluating the migration of intracoronary injected 99mTc-HMPAO labeled bone marrow CD34+ cells in subjects after myocardial infarction." (PMID 26880951, 2016). "Thirty-four patients who suffered myocardial infarction were randomly assigned to PC or OTW infusion of autologous bone marrow CD34+ cells labeled with 99mTc-HMPAO." (PMID 26880951, 2016). "In the current proof of concept study, we used human CD34+ cells to understand the beneficial effect of metformin on angiogenesis at 3 h of hypoxia, as this is a therapeutic window in the management of acute myocardial infarction." (PMID 26861446, 2016). "To further explore the safety and efficacy of BiAb targeting of CD34+ cells, we investigated the effects of antibody targeted CD34+ cells on myocardial conduction following a myocardial infarction (MI) and its long-term effects on LV function." (PMID 25904069, 2015). "This study aimed to evaluate the possible role of Avemar or Echinacea extracts in inducing mobilization and homing of CD34+ stem cells in relation to the inflammatory and hematopoietic cytokines in rats suffering from acute myocardial infarction (AMI)." (PMID 26369808, 2015). "Several clinical trials are exploring therapeutic effect of human CD34+ cells in ischemic diseases, including myocardial infarction." (PMID 26553339, 2015). "Because LPA-treated CD34+ cells were injected in a myocardial infarction animal model in a fibrin gel, we evaluated their secretome." (PMID 26553339, 2015). "Meneveau and co-workers have shown that the level of circulating CD34+/VEGF-R2+ cells correlates with the number of BOEC colonies in patients with acute myocardial infarction." (PMID 24955753, 2014). "This phenomenon recalls the surge of CD34+ progenitor cells 3-5 days after tissue damage (e.g., myocardial infarction)." (PMID 23992307, 2013). "In patients with extensive myocardial infarction, apoptotic progenitor cells (CD34+/AV+) were increased, suggesting that progenitor CD34+ cells are mobilized from the bone marrow but destroyed by apoptosis due to increased oxidative stress." (PMID 22615882, 2012). "In summary, the data shown in the present study identify a possible novel strategy to enhance the protective ability of human CD34+ cells against the consequences of myocardial infarction." (PMID 21789227, 2011). "Therapeutic potential was evaluated in a rat model of myocardial infarction using nanofiber-expanded human cord blood derived hematopoietic stem cells (CD133+/CD34+) genetically modified with VEGF plus PDGF genes (VIP)." (PMID 19809493, 2009). "ANXA3 and SOCS3, as novel biomarkers for acute myocardial infarction (AMI), demonstrates significantly superior diagnostic performance compared to traditional markers CD34 and FLT3, with area under the ROC curve (AUC) exceeding 0.7, highlighting their stronger clinical relevance." (PMID 40760666, 2025). "Faiez Zannad from France presented the results of the Phase 1/2b EXCELLENT trial, demonstrating that intramyocardial injections of autologous expanded CD34+ stem cells (ProtheraCytes) for the treatment of Acute Myocardial Infarction (AMI) promote reverse remodeling." (PMID 39749331, 2024).
myocardial infarction (continued). "Cardiac repair potentially induced by CD34+ cells delivered intramyocardially as a therapy for myocardial infarctions could, thus, be the result of three intricate mechanisms." (PMID 37298503, 2023). "Moreover, miR-378 regulates the proangiogenic and paracrine capacities of CD34+ progenitor cells activated in acute myocardial infarction." (PMID 34099038, 2021). "This may suggest that myocardial infarction potentially induces the bone marrow to mobilize EPCs and CD34+ mononuclear cells to repair the infarction induced vascular damage." (PMID 33193725, 2020). "Similarly, in myocardial infarction rat models, injection of human CD34+ BM-derived EPCs followed by G-CSF administration has been shown to differentiate into ECs." (PMID 33193725, 2020). "The relationship between B2R expression on circulating CD34+ cells and prognosis of myocardial infarction remains unknown." (PMID 31360266, 2019). "We suggest a hypothesis that expression of B2R on circulating CD34-positive cells has the relationship to the prognosis of myocardial infarction." (PMID 31360266, 2019). "Indeed, moderate-dose atorvastatin increased CD34+ cells in patients with myocardial infarction, and systemic rHDL infusion can improve the availability of CD34+ cells in patients with type 2 diabetes." (PMID 28060837, 2017). "The longitudinal study of patients with myocardial infarction showed a decreasing trend of the number of circulating CD34+ cells, which at day 7 was statistically lower than at admission, although it was higher than that of controls and became comparable to that of controls within 60 days." (PMID 26839569, 2016). "Indeed, CD34+ cells genetically modified to express Shh [CD34+(Shh)] offer a better protection against ventricular dilation and cardiac functional decline than CD34+ cells alone when injected into mice after acute myocardial infarction." (PMID 25136343, 2014). "Moreover, our group observed an association between enhanced platelet SDF-1 expression with reduced left ventricular function and the number of circulating CD34+ progenitor cells, predominantly in patients suffering from acute myocardial infarction (MI)." (PMID 24834915, 2014). "Notably, it has been shown that patients with acute myocardial infarction have increased numbers of CD34+/VEGFR2+ progenitor cells, that correlate with plasma VEGF levels." (PMID 22506045, 2012). "The 100-day mortality was 9.6% (3 of 31 transplants); Two patients died at day +9 and +11 as a result of sepsis during granulocytopenia and one died at day +100 due to a myocardial infarction; they had received 2.5, 1.5 and 3.4 x 106 CD34 +ve viable cells / Kg, respectively." (PMID 21415967, 2010). "Moreover in rat myocardial infarction models, collaterals and improved cardiac function have been demonstrated using CD34+ stem cell therapy." (PMID 19809493, 2009). "CD34+ cells alone or as part of bone marrow aspirate have been used as novel stem cell therapies in the treatment of acute myocardial infarction (MI) or heart failure with beneficial effect." (PMID 26861446, 2016). "Therefore, we studied vasoreparative properties of CD34+ cells following incubation with physiological concentration of metformin, under conditions of hyperglycemia, and/or hypoxia as a model of intervention window during acute myocardial infarction." (PMID 26861446, 2016). "In particular, a favorable improvement in left ventricular (LV) function in a rat model of myocardial infarction (MI) after intravenous injection of ex vivo expanded human CD34+ cells has been reported." (PMID 26509164, 2015). "However, after myocardial infarction (MI), Pdpn is upregulated in a heterogeneous cell population such as PDGFRα-, PDGFRβ-, and CD34-positive cells, besides lymphatic endothelial cells." (PMID 36970507, 2023).
myocardial infarction (continued). "According to data from a mouse model of experimental acute myocardial infarction (AMI), human CD34+ cells imbedded in the hypoxic/ischemic region and shifted toward cardiomyocytes and ECs, which related to improved heart utility." (PMID 37138792, 2023). "The in vivo experiment further confirmed the enhanced EPC recruitment, in which we used two EPC markers, CD34 and VEFGFR2, for colocalization staining to quantitatively analyze the number of EPCs in the peripheral area of the myocardial infarction." (PMID 37055411, 2023). "In the recent outcome analysis of the phase 3 clinical PERFECT trial we are investigating intramyocardial transplantation of c-KIT/CD117+/CD133+,/CD34+ bone marrow derived hematopoeitic stem cells (BM-HSC) in post-myocardial infarction (MI) coronary artery bypass graft (CABG) patients." (PMID 32629392, 2020). "Temporary downregulation of adaptor gene SH2B3 in cKIT-CD117+/CD133+/CD34+ HSC can be a therapeutic switch to improve downregulated stem cell response in ischemia, tissue repair, and myocardial infarction." (PMID 32629392, 2020). "Circulating levels of CD34+ cells predict advanced CAD, physical function, adverse clinical outcomes after myocardial infarction, and overall survival." (PMID 32823683, 2020). "We analyzed the expression of B2R on circulating CD34-positive cells and plasma VEGF concentration in 174 myocardial infarction patients." (PMID 31360266, 2019). "It has been previously shown that CD34+/VE-cadherin+ cells derived from induced pluripotent stem cells release pro-angiogenic and anti-apoptotic factors, which may contribute to the recovery of cardiac function following myocardial infarction seen in the present study." (PMID 28781077, 2017). "We have shown, both in a mouse model of hindlimb ischemia and myocardial infarction, that MSC with CD105+CD34- phenotype exhibit therapeutic properties." (PMID 27415778, 2016). "The levels of these cytokines were found to be significantly higher in patients with acute myocardial infarction (AMI) and were correlated positively with the number of circulating CD34+ SCs." (PMID 26369808, 2015). "There was a significant positive correlation between CD34+CXCR4+ cells mobilization and left ventricle ejection fraction in first 24 hours after myocardial infarction (r = 0, 39, P = 0,03)." (PMID 22547906, 2012). "In 25 control subjects, 65 patients with coronary artery disease (CAD; 40 stable CAD, 25 acute coronary syndrome/acute myocardial infarction (ACS)), EPC were quantified using the following approach: Whole blood was incubated with CD45, KDR, and CD34." (PMID 21072182, 2010). "Likewise, a rapid and significant increase in EPC numbers, detected by utilising 5 different approaches (CD34+, D34+/CD117+, CD34+/CXCR4+, CD34+/CD38+ and CD34+/CD45+), has been reported after the onset of ischemia in acute myocardial infarction." (PMID 24267290, 2013). "Although the majority of the clinical trials have been in patients with no-option refractory angina, CD34+ stem cells have also been investigated in clinical studies for peripheral ischemia, nonischemic cardiomyopathy, myocardial infarction, and ischemic stroke." (PMID 34066713, 2021). "Interestingly, although the benefits of CD34+ve exosomes on angiogenesis have been observed, CD34+ve hematopoietic stem cells do not have cardioprotective effects in the expression of the SHH gene after acute myocardial infarction." (PMID 32724810, 2020). "Interestingly, despite the benefit of CD34+ve exosomes observed on angiogenesis, CD34+ve hematopoietic stem cells were not cardioprotective when administered after acute myocardial infarction unless engineered to express sonic hedgehog (Shh)." (PMID 27796607, 2017). "In our study, both in the mouse model of hindlimb ischemia and myocardial infarction, we did not notice, however, rejection of transplanted human CD105+CD34- cells by the host organism." (PMID 27415778, 2016).
myocardial infarction (continued). "Moreover, the transient increase in CD34/45+ and CD133/45+ BM-CPCs reached a maximum after three weeks of regular symptom-limited (ischemic and/or subischemic) exercise training, but did not persist until 3 months after the regular training after acute myocardial infarction." (PMID 22118372, 2011). "The hypothesis of cardiac homing in the absence of acute myocardial infarction was recently confirmed in two Phase I cardiac cell therapy clinical trials on patients with chronic ischemic cardiomyopathy and receiving an intracoronary injection of radiolabeled CD133+ or CD34+ cells." (PMID 20504285, 2010).